GAS5 (growth arrest specific 5)
Diseases named in the same sentence as GAS5 in open-access papers (continued):
Sharing a sentence is not in itself a finding about the gene and the disease.
tumor (continued). "GAS5 expression has been examined in a variety of human cancers, and its levels have been found to be lower in cancer tissues than in adjacent non-tumor tissues." (PMID 37444428, 2023). "A xenograft model of GAS5 overexpression (OE) showed that GAS5 OE markedly decreased tumor size compared with control." (PMID 37370745, 2023). "The expression of tumor suppressor LncRNAs including GAS-5 and MEG3 was significantly augmented in bharangin-treated cells, while this diterpenoid down-regulated oncogenic H19 LncRNA." (PMID 36770654, 2023). "We have observed that SMG7 is required for targeting GADD45b and the tumor suppressor lncRNA GAS5 for degradation in our cells." (PMID 37349371, 2023). "A xenograft mouse model of GAS5 overexpression (OE), GAS5 OE plus gefitinib, gefitinib alone, or vehicle, showed that GAS5 OE plus gefitinib yielded the best tumor size reduction outcomes." (PMID 37370745, 2023). "Tumor-suppressive lncRNAs include growth arrest-specific transcript 5 (GAS5), MEG3, DGCR5, PTENP1, and NKILA." (PMID 38094755, 2023). "Low GAS5 levels promoted tumor angiogenesis, while high levels of GAS5 resulted in inhibited proliferation and tube formation, and increased apoptosis." (PMID 36905871, 2023). "It has also been indicated that GAS5 can suppress MYC expression, suggesting another mechanism through which GAS5, at least partly, induces its tumor-suppressive effect." (PMID 37624036, 2023). "Comparable to tumor-promoting lncRNAs, tumor-suppressive lncRNAs such as GAS5 also show potential as biomarkers in NSCLC." (PMID 37370745, 2023). "The lncRNA growth-arrest-specific transcript 5 (GAS5) is widely reported as a tumor suppressor gene." (PMID 35782387, 2022). "The use of PI3K activators was found to reverse the inhibitory effect of GAS5 overexpression on tumor proliferation and migration, suggesting that GAS5 inhibits tumors by inactivating the PI3K/AKt/mTOR pathway." (PMID 35241975, 2022). "Growth arrest‐specific 5 (GAS5) is known as a tumor suppressor, negatively regulating cell survival and malignancy in different cancer cell types." (PMID 35813295, 2022). "The GAS5 SNP rs145204276 Ins/Del + Del/Del illustrated a higher distribution with an advanced tumor stage (p = 0.030), larger tumor T status (p = 0.019), positive lymph node status (p = 0.014) and distal metastases (p = 0.011) in the EGFR wild type group." (PMID 36011604, 2022). "Although many tumor-suppressing lncRNAs are under investigation, the most documented are the growth arrest-specific transcript 5 (GAS5), the maternally expressed gene 3 (MEG3), and the NF-kB interacting lncRNA (NKILA)." (PMID 35978835, 2022). "In BC, lncRNAs are emerging as master regulators of tumour biology, with oncogenic functions associated with tumorigenesis and tumour progression (HOTAIR, MALAT-1, lincRNAp21, and GAS5)." (PMID 35525949, 2022). "As a result, GAS5 expression levels in tumor tissues are significantly reduced, leading to increased malignancy, poor prognosis, and drug resistance." (PMID 35837102, 2022). "Previous studies have reported that lncRNA GAS5 was a tumor suppressor and overexpression of lncRNA GAS5 inhibited tumor progression by activating YAP phosphorylation." (PMID 35435104, 2022). "Another important tumor-suppressor lncRNA involved in autophagy activation is the growth arrest-specific 5 RNA (GAS5)." (PMID 35978835, 2022). "As is the case with CLL, in AML GAS5 exerts its tumor-suppressor function, acting as a decoy for miR-222." (PMID 36362925, 2022). "The growth arrest-specific 5 (GAS5) is a type of long non-coding RNA that acts as a tumor suppressor and influences the cell apoptosis and tumorigenesis processes in accordance with previous publications." (PMID 36011604, 2022). "GAS5 is a typical tumor suppressor LncRNA; it has been found to have a significant ability to inhibit tumor cell proliferation and promote apoptosis in lung, breast, and colorectal cancer." (PMID 35241975, 2022).
tumor (continued). "Taken together, the lncRNAs in common (EBLN3P, AC004542.2, ZFAS1, and GAS5) seemed the most potentially predictive or prognostic genes for PCa that were closely related to the tumor progression." (PMID 36514044, 2022). "The results showed that AC005261.1, LINC01578, ZFAS1, EBLN3P, THUMPD3-AS1 and GAS5 were highly expressed in tumor than adjacent normal samples." (PMID 36514044, 2022). "GAS5 is down-regulated in many types of cancer indicating a tumor-suppressor function of this lncRNA." (PMID 36362925, 2022). "(VIII) Acting as a tumor suppressor; lncRNA growth arrest-specific 5 (Gas5) targets cancer-promoting miRNAs such as miR21 and plays a role as a tumor suppressor in T and B cell leukemia." (PMID 35359941, 2022). "GAS5 acts as a “sponge-like” to interact with miRNA molecules, binds to one or more functional proteins, and limits tumor angiogenesis." (PMID 35837102, 2022). "Based on these findings, we indicated that the low expression of GAS5 in tumor cells promoted the biological progression of CRC." (PMID 36062165, 2022). "Growth arrest-specific 5 (GAS5) is located at 1q25.1 and was originally identified in a study aimed to screen for novel tumor suppressor genes expressed at high levels during growth arrest." (PMID 35207562, 2022). "Animal experiments showed that when mice were irradiated with 6 MV X-ray 16Gy/4F, the tumor size of the GAS5-overexpressing group was significantly reduced, while that of the GAS5 knockdown group was significantly increased." (PMID 35692795, 2022). "A series of studies have shown that GAS5 plays a tumor-suppressive role by regulating the growth, death, migration, and invasion of cancer cells." (PMID 36672566, 2022). "GAS5 (growth arrest-specific 5) is a lncRNA that was first discovered as a cancer tumor suppressor gene." (PMID 36310591, 2022). "This increase in GAS5 expression in ESCC cells also promotes the interferon response in tumor cells and up-regulates the levels of IFN." (PMID 35241975, 2022). "For example, lncRNA GAS5 in TNBC patients is related to tumor resistance to PTX, which induces apoptosis by regulating the miR-378a-5p/SUFU signal pathway." (PMID 36387210, 2022). "In Wang’s study, GAS5 was lower in tumor tissues than that in healthy tissues, and the serum GAS5 level in EC patients was significantly lower than that in normal controls." (PMID 35645836, 2022). "Our research provides new evidence to support a new regulatory pathway where GAS5 plays a key role in tumor metastasis and invasion." (PMID 36062165, 2022). "Recently, growth arrest-specific 5 (GAS5) lncRNA has been found to be a tumor suppressor for modulating energy homeostasis in cells." (PMID 35163579, 2022). "Expression analyses from the other two independent datasets (GSE29079, GSE94767) showed four (AC004542.2, ZFAS1, EBLN3P, GAS5) out of nine lncRNAs were significantly overexpressed in tumor." (PMID 36514044, 2022). "GAS5 expression was associated with the clinicopathological characteristics of CRC, and patients with high GAS5 expression had a smaller tumor diameter and early TNM staging." (PMID 35837102, 2022). "Dysregulated lncRNA growth arrest-specific 5 (GAS5) was reported to be involved in tumor propagation, metastasis, as well as EMT in osteosarcoma." (PMID 35697671, 2022). "Regarded as a tumor suppressor, GAS5 regulates cellular proliferation, invasion and metastasis in various types of human tumors." (PMID 35957809, 2022). "LncRNA growth arrest-specific transcript 5 (GAS5) acts as a pivotal tumor suppressor in various types of human cancers." (PMID 36438563, 2022). "Growth arrest-specific 5 (GAS5) was initially shown to regulate cell proliferation and cell cycle during embryogenesis and tumor progression." (PMID 36685879, 2022). "The lncRNA GAS5 evolved various strategies to regulate gene expression as vital tumor proliferation suppressor." (PMID 35837102, 2022).
tumor (continued). "The effects of GAS5, let-7e, and miR-125 on tumor cell growth in vivo were verified in nude mice after injection of GAS5 overexpressing U87 cells subcutaneously or stereotactically into the brain." (PMID 36106122, 2022). "In the subgroup analysis of the EGFR wild type population, the presence of GAS5 SNP rs145204276 Ins/Del + Del/Del was correlated to an advanced tumor stage (p = 0.014) and distal metastases (p = 0.020) in non-smokers." (PMID 36011604, 2022). "lncRNA growth arrest specific 5 (GAS5), located at chr1q25.1, has been reported to have tumor suppressive activity in multiple human cancers by modulating several cellular processes." (PMID 34771549, 2021). "The expression levels of GAS5 in the tumor tissues of 156 patients treated with PTX and CIS were also determined." (PMID 34202777, 2021). "In the current study, tumor suppressor lncRNA GAS5 was detected in exosomes derived from serum of CRC patients and non-cancer individuals." (PMID 34571795, 2021). "Although the expression level of GAS5 is increased during growth arrest by serum deprivation, in many types of cancer it was shown that GAS5 is down-regulated indicating a tumor suppressor function of this lncRNA." (PMID 35054253, 2021). "Functional studies revealed that lncRNA GAS5 acts as a tumor suppressor by inhibiting CRC cell proliferation, migration, and invasion." (PMID 34571795, 2021). "The expression of GAS5 is inversely correlated with tumor size, staging, and metastasis in several tumor types, including breast, bladder, colon, pancreas, and prostate cancer." (PMID 33435206, 2021). "GAS5 is induced under stress conditions such as serum starvation and cell-cell contact inhibition and has been reported to possess tumor-suppressive functions in humans." (PMID 33776993, 2021). "Regarding the aspect of GAS5, it was proven to alter the tumor expression in several types of neoplasms." (PMID 33925911, 2021). "For instance, lncRNA GAS5 (Growth arrest-specific 5), a tumor suppressor, functions as a sponge by sequestering and decreasing oncogenic effects of miR-21 and inhibits the proliferation of cancer cells and induces apoptotic cell death." (PMID 33672592, 2021). "In contrast, reduced levels of the lncRNA GAS5 in the same cell and tissue models enhanced tumor cell proliferation and resistance to trastuzumab via modulation of the miR-21/PTEN/mTOR axis." (PMID 34943820, 2021). "Due to the ability of GAS5 to induce apoptosis and suppress tumor growth, the relationship between GAS5 and a wide range of malignancies was evaluated." (PMID 33925911, 2021). "As a well-established tumor suppressor gene, GAS5 is shown to exert growth arrest effects in different types of cancer." (PMID 34094978, 2021). "SNHG2, also named growth-arrest-specific-5 (GAS5), is a host gene of many snoRNAs and is widely considered a tumour suppressor in numerous human neoplasms." (PMID 33968736, 2021). "Growth arrest-specific 5 (GAS5) lincRNA was identified as a poorly conserved tumor suppressor that also acts as a decoy for the glucocorticoid receptor (GR)." (PMID 34204634, 2021). "The decreased expression of GAS5 has been correlated with poor tumor differentiation, metastasis to the lymph nodes, advanced pathological stages, adverse overall survival, resistance to chemotherapy, and so on." (PMID 34760707, 2021). "Due to the antiproliferative effects and downregulation in numerous solid malignancies, a widely accepted tumor suppressor role has been attributed to GAS5." (PMID 34885174, 2021). "There is increasing evidence that lncRNA GAS5 acts as a tumor suppressor, which is downregulated in certain tumor tissues and combined with miRNA to regulate related signaling pathways." (PMID 34796177, 2021). "Previous studies have shown that Growth Arrest Specific 5 (GAS5) is a potential tumor suppressor and is down-regulated in a variety of cancers." (PMID 34199840, 2021).
tumor (continued). "GAS5 has been found as a tumor inhibitor in several cancer types, however, its pro-inflammatory roles have also been identified." (PMID 33645622, 2021). "Knockdown of GAS5 improves chemo-sensitivity and apoptosis in the tumor cells treated with 5-FU and DOX." (PMID 34425750, 2021). "Overexpression of GAS5 was shown to undermine the tumour promotion effect induced by ectopic expression of miR‐196a‐5p, including cell invasion and FOXO1/PI3K/Akt signal pathway activation." (PMID 33314471, 2021). "It was revealed that GAS5 was capable of repressing tumour cell viability and proliferation by blocking the protein kinase B (AKT)/mammalian target of rapamycin (mTOR) signalling pathway." (PMID 33968736, 2021). "Previous studies in cancer have suggested that GAS5 puts a “brake” on cell proliferation, thereby acting as a potential tumor suppressor in various cancers." (PMID 33776993, 2021). "In a study concerning the modulation of GAS5 in PCa radiotherapy GAS5 was found able to silence miR-18a to promote α-Solanine, a novel anti-tumour molecule able to increase tumour cell sensitivity to radiation." (PMID 33968736, 2021). "An independent research pointed out that lncRNA GAS5 was downexpressed in HCC tumor compared with normal tissue and interference of lncRNA GAS5 accelerated tumor cell migration by reducing NK cell cytotoxicity." (PMID 33968985, 2021). "It is reported that lncRNA growth arrest specific 5 (GAS5) is a tumor suppressor in multiple cancers including NSCLC." (PMID 34022918, 2021). "A functional role as a tumor suppressor has been previously reported for GAS5 in U87 (obtained from the Shanghai Institutes for Biological Sciences Cell Resource Center)." (PMID 34207434, 2021). "In normal cells, GAS5’s expression is low; however, in tumor tissues and other diseased tissues, GAS5 is upregulated." (PMID 35155450, 2021). "In contrast, enhancing miR-145 level significantly impeded tumour cell proliferation and induced apoptosis by elevating GAS5 expression." (PMID 33968736, 2021). "LncRNA growth arrest‐specific transcript 5 (GAS5) is a well‐known tumour suppressor gene in several human cancers." (PMID 34405957, 2021). "GAS5 also inhibited tumor inducer miR-196-5p, which led to suppressed tumor growth by positive regulation of tumor suppressors forkhead box protein O1 (FOXO1) and phosphotyrosine interaction domain containing 1 (PID1)." (PMID 34322395, 2021). "The tumor suppressor gene lncRNA growth arrest‐specific 5 (GAS5) and MEG3 have been found to inhibit autophagy by suppressing the cleavage of LC3, thereby enhancing the chemosensitivity of lung cancer cells." (PMID 33931980, 2021). "lncRNA GAS5 regulates NK cells cytotoxicity, tumor cell apoptosis, and tumor aggressiveness via miR-544/RUNX in liver cancer." (PMID 33763348, 2021). "In the same study, GAS5 sensitized tumor cells to ultraviolet (UV) irradiation and the chemotherapy drug doxorubicin." (PMID 34202777, 2021). "In vivo experiments with MCF7-R cells treated with tamoxifen and transfected with a vector overexpressing a GAS5 cDNA into nude mice decreased tumor growth." (PMID 34359587, 2021). "For instance, GAS5 regulated the expression of tumor suppressors Bcl-2-modifying factor (Bmf) and Plexin C1 via targeting miR-222, which led to inhibition of tumor progression." (PMID 34322395, 2021). "Upregulation of Gas5 dramatically inhibited the cell proliferation and the tumor growth in PTC by the activation of PTEN/AKT pathway via sponging miR-222-3p." (PMID 34281460, 2021). "Given the tumor-suppressive nature of GAS5, miR-21 should be oncogenic, and reports on miR-21 confirm such oncogenic role of this miRNA." (PMID 34386496, 2021). "The tumor size of sh-GAS5 group was obviously enlarged compared with the tumors in control group and overexpression group." (PMID 33976738, 2021).
tumor (continued). "The decreased expression of lncRNA GAS5 has been correlated with the clinical characteristics of the tumor, such as metastasis to the lymph nodes, tumor recurrence, decreased survival rates, and resistance to chemotherapy." (PMID 34202777, 2021). "GAS5 expression was found to be upregulated and miR-217 expression was found to be reduced in tumor tissues containing LV-GAS5." (PMID 33418541, 2021). "As such, GAS5 participates in tumor growth, proliferation, invasion, metastasis inhibition, as well as the induction of apoptosis." (PMID 33076450, 2020). "The general consensus is that GAS5 acts as a tumor suppressor across different tumor types and that its up-regulation results in tumor sensitization to chemotherapy or radiotherapy." (PMID 33076450, 2020). "GAS5 is one of the few lncRNAs that are negatively correlated with tumor development in breast cancer, malignant pleural mesothelioma and hepatocellular carcinoma." (PMID 32257946, 2020). "LncRNA GAS5 has been proved to be a tumor suppressor in many studies via directly sponging miR-21 and enhancing chemotherapy sensitivity." (PMID 32122355, 2020). "As expected, the tumour volumes in the lentivirus-GAS5 group were significantly smaller than those in the lentivirus-NC group." (PMID 32661236, 2020). "When GAS5 is downregulated, it acts as a tumor-suppressor in several types of cancers, such as colorectal, breast, prostate, lung and ovarian cancers." (PMID 33371204, 2020). "Although early diagnosis is of paramount importance for the treatment and prognosis of this tumor, there is still a lot to understand on the mechanisms of action of GAS5 in it." (PMID 33076450, 2020). "GAS5 has been reported as a tumor suppressor in some cancers, and it is related to the proliferation, apoptosis, and migration of tumor cells in breast cancer, stomach cancer and prostate cancer." (PMID 32326098, 2020). "GAS5 was reported as one of the ncRNAs that is regulated by phytochemicals, which can synergistically affect tumor development and progression." (PMID 33076450, 2020). "GAS5 seems to play a previously unappreciated, but significant role in tumor therapy-induced resistance." (PMID 33076450, 2020). "Overexpression of GAS5 appeared as a strategy for the tumor therapeutics via inducing apoptosis and concomitant attenuated cell proliferation." (PMID 33362791, 2020). "A significant decrease in the tumour volume was observed macroscopically in the lentivirus-GAS5 group, and one of the tumours had even disappeared." (PMID 32661236, 2020). "In the present study, we explored the expression of GAS5 along with that of various miRNAs across different tumor types and focused on its role in therapy-related sensitivity to these cells." (PMID 33076450, 2020). "The main conclusion is that GAS5 seems to exert a tumor-suppressive role in the process of carcinogenesis across all tumor types." (PMID 33076450, 2020). "In this study, it was also found that GAS5 over-expression was related to the inhibition of leukemic cells proliferation, the enhancement of leukemic cell apoptosis and the inhibition of tumor cell invasion." (PMID 33076450, 2020). "Yet, all studies agree that GAS5 acts as a suppressor or “sponge” for oncogenic miRNAs, whereas its overexpression is closely related to tumor suppression and induction of therapy-related sensitivity." (PMID 33076450, 2020). "Recent work has shown that lncRNA GAS5 is dysregulated in multiple human cancers and confirms a tumor suppressor role." (PMID 32194641, 2020). "Despite the achievement in field of tumor research, there are few studies about GAS5 on pregnancy related diseases." (PMID 32194641, 2020). "The tumor suppressive effects of PTEN in the ceRNA network have also been reported in conjunction with growth arrest-specific 5 (GAS5), Itchy E3 Ubiquitin Protein Ligase (Circ-ITCH), Fer-1-like protein 4 (FER1L4)." (PMID 32906679, 2020).